FABP5 (fatty acid binding protein 5)
Diseases named in the same sentence as FABP5 in open-access papers (continued):
Sharing a sentence is not in itself a finding about the gene and the disease.
tumor (continued). "More recently, the same group showed that FABP5 inhibitors suppress PCa tumor formation and metastasis by inhibiting fatty acid uptake and PPARγ expression." (PMID 33352874, 2020). "These six CD302/FABP5 correlated genes were reported to be involved in tumor cell proliferation, migration, invasion and EMT." (PMID 32775301, 2020). "Our previous work showed that the structural integrity of this fatty acid-binding motif is essential for the tumour-promoting function of FABP5." (PMID 31258834, 2019). "Ex vivo analysis of primary tumor mass and luciferase signal in femurs and lungs confirmed reduced tumor growth and metastasis in these FABP5 knockdown cells." (PMID 31831821, 2019). "Such markers include adipocytokines like omentin, fatty acid binding protein 5 (FABP5), and granulin; miRNAs; circulating tumor cells (CTCs); and plasma or urine-derived cell-free RNA and DNA." (PMID 31915468, 2019). "This was also the case with Fabp5 mRNA and protein, where only the former was found to be different in the tumor tissues between the two groups." (PMID 31905933, 2019). "Its biological effects are largely determined by two classical signaling pathways mediated by Cellular retinoic acid binding protein 2 (CRABP2) or Fatty acid-binding protein 5 (FABP5), which results in tumor suppression or tumor promotion." (PMID 31736873, 2019). "PC3-M cells were inoculated into the right flank of nude mice and the FABP5 inhibitor dmrFABP5 was injected subcutaneously to compare its tumor-suppressing effect with those of PPARγ antagonists and the chemical inhibitor SB-FI-26." (PMID 31258834, 2019). "Designing highly selective inhibitors of fatty acid binding proteins 4 and 5 (FABP4 and FABP5) is of importance for treatment of some diseases related with inflammation, metabolism, and tumor growth." (PMID 30142969, 2018). "Tumor cells were transfected with FABP5-targeting siRNA, and cells were harvested at day 6 after transfection for western blotting." (PMID 29914512, 2018). "Since the retinoid binding affinity of the CRABP2-RAR pathway is higher than that of the FABP5-PPARβ/δ pathway, at least a partial ATRA-mediated tumor-suppressive effect is expected in tumors with comparable FABP5 and CRABP2 expression." (PMID 30384831, 2018). "We subsequently investigated expression of PRDX1, FMNL, NCL, CLIC3, FLNA, PHB2, and FABP5 of 229 ESCC tumor tissues by TMA." (PMID 29683265, 2018). "We revealed a significant role of FABP5 in tumor progression, invasion and metastasis of HCC through the induction of EMT." (PMID 28374947, 2017). "SBFI26 as a lead inhibitor of FABP5 showed efficient anti-tumour roles in the mouse model for primary tumours implanted in the prostate gland (by 4.9- fold) and inoculated in the flank (by 52%)." (PMID 28415688, 2017). "Our study demonstrated that overexpression of FABP5 promoted cell proliferation, invasion, and migration in vitro and also promoted tumor growth in mice models." (PMID 28374947, 2017). "In our studies, we show FABP5 in the TNBC tumor cell as well as the host is important for metastasis of TNBC." (PMID 25779666, 2015). "FABP5 plays a dual role, in the tumor cell and the host, in breast cancer tumor growth and metastasis." (PMID 25779666, 2015). "Using a FABP5−/− mouse model, host FABP5 was found to be important for tumor progression and metastasis." (PMID 25779666, 2015). "CRABP2 and FABP5 were expressed in hair follicles of lid skin in both groups, whereas the CRABP2 and FABP5 were aberrantly expressed in the tumor cells of the sebaceous glands." (PMID 26503156, 2015). "For example, it was reported that the expression ratio of FABP5 to CRABP-II was significantly higher in the tumor tissues of short-term survivors compared to long-term survivors." (PMID 25797252, 2015). "The role of FABP5 in tumor progression was assessed via in vivo experiments." (PMID 41035647, 2025).
tumor (continued). "Similarly, targeting FABP5, a lipid chaperone upregulated by tumor‐derived IL‐10, decreases lipid storage in TAMs and restores β‐oxidation rates, countering chemotherapy resistance in hepatocellular carcinoma." (PMID 40904700, 2025). "Importantly, the inhibition of FABP5 amplified and sustained the anti‐tumor immune response induced by RFA, with the activation of the STING/TBK1 pathway playing a critical role." (PMID 40956367, 2025). "Additionally, from a metabolic perspective, FABP5 functions as a critical mediator of tumor progression." (PMID 40956367, 2025). "However, FABP5 expression significantly corelated with tumor grade, tumor metastasis and patient vital status." (PMID 40106183, 2025). "In addition, in tumor cells overall expression of FABP5 (47.2 ± 60.46) was significantly higher than that of FABP4 (8.49 ± 18.24)." (PMID 40106183, 2025). "Notably, in multiple specimens with tumor metastases, we observed that tumor cells within blood vessels in the primary tumors exhibited strong expression of FABP5 expression, suggesting a possible pro-metastatic activity of FABP5 in tumor cells." (PMID 40106183, 2025). "Based on our datasets, we found that FABP5 mRNA expression showed a significant difference between the adjacent and tumor tissues with VHL mutation, but not in the VHL wild‐type samples." (PMID 40391655, 2025). "Therefore, genetic targeting of FABP5 not only directly suppresses the malignant phenotype of tumor cells but, more importantly, specifically reverses FABP5‐mediated immune metabolic dysregulation." (PMID 40956367, 2025). "Mechanistically, FABP5 may drive tumor progression through PPARβ/δ signaling, epithelial‐mesenchymal transition induction, angiogenesis regulation, and potential effects on fatty acid metabolism and hypoxia‐related pathways." (PMID 40178066, 2025). "The upregulation of FABP5 in high-risk GBM patients, as seen in our analysis, suggests that it may facilitate the metabolic reprogramming of TAMs to sustain tumor-promoting functions." (PMID 41164132, 2025). "FABP5 inhibitors (e.g., orlistat) significantly suppress tumor growth and metastasis, and may enhance the efficacy of immunotherapy." (PMID 40717587, 2025). "By focusing on the specific communication axis through which HCC cells regulate TAM lipid metabolism and immune phenotype via exosomal FABP5, this research is expected to unveil a new dimension of the complex interaction network within the tumor microenvironment." (PMID 41035647, 2025). "Their research showed that SBFI-103, a small drug targeting FABP5, successfully suppressed tumor development in preclinical animals, providing further evidence that FABP5 inhibition may circumvent resistance pathways linked to PTEN depletion." (PMID 41009695, 2025). "In contrast, FABP5 expression in estrogen receptor (ER)-negative cancer cells was shown to promote tumor growth and is associated with a poor prognosis." (PMID 40106183, 2025). "However, clinical translation faces challenges, including FABP5’s physiological roles in normal tissues (e.g., lipid metabolism regulation), tissue-specific regulatory mechanisms, and tumor microenvironment effects (e.g., stromal fibrosis)." (PMID 40717587, 2025). "In addition, natural compounds, such as oleanolic acid and pterostilbene, have also been shown to modulate FABP3- and FABP5-related oncogenic pathways, restoring drug sensitivity and suppressing tumour cell migration, respectively." (PMID 41149452, 2025). "FABP5 expression was significantly higher in tumor tissues than in normal tissues." (PMID 40956367, 2025). "While FABP5 expression demonstrated a stronger correlation with tumor differentiation in two studies conducted outside of China (specifically in Korea and Japan), the significance of this finding is diminished by the differing geographical origins of these studies." (PMID 40178066, 2025).
tumor (continued). "Additionally, patients with HCC exhibiting high FABP5 expression demonstrated a higher degree of malignant progression, implicating FABP5 in tumor advancement." (PMID 40956367, 2025). "FABP5 plays an oncogenic role in pancreatic neuroendocrine neoplasms (pNENs), where it is consistently overexpressed in tumour tissues and cell lines and promotes proliferation, migration, invasion, and tumour growth both in vitro and in vivo." (PMID 41149452, 2025). "FABP5 may also promote tumor cell energy production by regulating the AMP to ADP/ATP ratio, protein kinases, and the number of autophagosomes." (PMID 40178066, 2025). "In addition to its effects on the immune system, LA directly promotes oncogenic signaling within tumor cells through fatty acid-binding protein 5 (FABP5), a cytosolic chaperone for hydrophobic molecules, converting it into an activator of oncogenic signaling." (PMID 41583314, 2025). "In contrast, FABP5, primarily expressed in epithelial-derived tumor cells, could promote tumor metastasis by enhancing lipid metabolism." (PMID 40106183, 2025). "The paradoxical role of FABP5 across different cancers may be influenced by tumor microenvironmental context." (PMID 40717587, 2025). "The FABP5-HIF-1 axis also promotes tumor spheroids’ growth of CRC cells." (PMID 39125923, 2024). "In line with other studies showing a correlation of high FABP5 expression with poor prognosis and metastasis in different tumor types, the brain-typed FABP5, which participates in long-chain fatty acid uptake, transport and metabolism was highly upregulated at the RNA and protein level in FIA10." (PMID 38215076, 2024). "Moreover, the maturation of lung-derived NK cells decreased in tumor-bearing Fabp5−/− mice, likely due to the reduced expression of T-bet and Eomes transcription factors." (PMID 38983267, 2024). "It was shown that FABP5 mRNA levels were much higher in the tumor, in comparison to the baseline level of the adjacent hepatic parenchyma, and the levels of FABP5 and vascular endothelial growth factor (VEGF) were also higher in the tumoral tissue when compared to the normal tissue surrounding it." (PMID 38927059, 2024). "But, the expression of FABP5 was found to be little related to tumor staging." (PMID 39194582, 2024). "EVs secreted by invasive tumoroids (3D d10‐d14) included proteins promoting tumour growth (solute carrier family 12 member 2, SLC12A2; sodium bicarbonate cotransporter 3, SLC4A7), tumour invasion (fatty acid binding protein 5, FABP5) and immunosuppression (cluster of differentiation 73, CD73)." (PMID 38938900, 2023). "Fatty acid-binding proteins (FABPs) are generally involved in the trafficking of lipids, and Fabp5 in particular has been shown to be induced in tumor-infiltrating MDSCs relative to splenic MDSCs and immature myeloid cells, indicating its induction in MDSCs within inflammatory environments." (PMID 37744359, 2023). "Moreover, NBASP negatively regulated fatty acid-binding protein 5 (FABP5) thus affected fatty acid metabolism to act as tumor-suppressing effect." (PMID 37438449, 2023). "For instance, the elevated expression of fatty acid-binding protein 5 (FABP5), nucleolar and spindle associated protein 1 (NUSAP1), and the oncoprotein cancerous inhibitor of protein phosphatase 2 (CIP2A) in the tumor tissue of CC patients is significantly associated with lymph node metastasis." (PMID 37234990, 2023). "Our study verified the negative association between miR-22-3p and FABP5 in one tumor type for the first time, presenting a great novelty and providing a new direction for molecular mechanism exploration in other tumor types with high FABP5 expression." (PMID 36906605, 2023). "Moreover, the potential relationships of FABP5 expression with immune cell infiltration and immune checkpoints in multiple tumor types were investigated." (PMID 36906605, 2023).
tumor (continued). "The recent demonstration that FABP5 inhibitors produce synergistic inhibition of tumor growth when combined with taxane chemotherapeutics highlights the possibility that FABP5 may regulate other features of taxane function, including resistance." (PMID 37796964, 2023). "Moreover, FABP5 promotes tumor angiogenesis and activates the IL6/STAT3/VEGFA pathway in HCC, as evidenced by studies." (PMID 37576389, 2023). "Moreover, survival analysis showed an association between high FABP5 expression and poor prognosis in several tumor types, suggesting potential prognostic values of FABP5 in those tumors." (PMID 36906605, 2023). "Interestingly, we found that the distribution of Scissor+ tumor cells, FABP5+ macrophages, and COL1A1+ CAFs in different subtypes corresponded with their clinical prognostic outcomes." (PMID 37021816, 2023). "Furthermore, an in vivo assay showed NBASP inhibited tumor growth, and that FABP5 restored anti-cancer activity." (PMID 37438449, 2023). "Furthermore, up-regulation of FABP5 in NBASP over-expressing cells reversed the anti-tumor effect of NBASP." (PMID 37438449, 2023). "FABP5 is also essential for cell cycle progression, migration, and tumor growth in vivo." (PMID 37781711, 2023). "Conversely, the down-regulation of FABP5 could reverse the increase in lipid metabolism and tumor growth." (PMID 37858219, 2023). "Thus, we did not include this tumor type in the scope of this study for the time being, and the subsequent analyses for FABP5-related upstream regulatory networks mainly focused on the other two tumor types." (PMID 36906605, 2023). "Overall, our collective findings offer valuable insights into the critical role of the ALKBH5/FABP5/FASN/mTOR axis in tumor progression and uncover a potential mechanism linking lipid metabolism to development of CRC, providing novel therapeutic targets for future interventions." (PMID 37416772, 2023). "Additionally, the prognostic value of FABP5 in several tumor types has also been revealed by several studies." (PMID 36906605, 2023). "More importantly, Mac.FABP5 showed higher spatial co‐localization with tumor cells than Mac." (PMID 37632718, 2023). "For each tumor sample, a prognostic risk score was computed employing the equation below: prognostic risk score = PAG1 expression × 0.2399877 + LHFPL2 expression × 0.2969381 + FABP5 expression × 0.2441960 (TCGA)." (PMID 37589508, 2023). "Furthermore, the recruitment of tumor-killing effector cells, especially NK cells, is enhanced by the expression of FABP5 in TAMs." (PMID 35445019, 2022). "FABP4 and FABP5 have the capacity to regulate transcription and may regulate tumor progression through both FA metabolism and/or the modulation of gene expression." (PMID 35721518, 2022). "In addition to its important role in tumorigenesis, FABP5 is also closely correlated with tumor grade and metastasis." (PMID 35445019, 2022). "This shows that FABP5 is essential in regulating host immune responses to tumor challenge and that host expression of FABP5 may represent a new anti-cancer protective factor by strengthening the antitumor activity of TAMs." (PMID 35445019, 2022). "Additionally, both qRT‐PCR and western blot analysis demonstrated that FABP5 was highly expressed in early passages of patient tumour‐derived LGGs primary cultures compared to normal human astrocytes." (PMID 33837625, 2021). "However, by using RNA ISH (RNAscope technology), we showed that there was reduced expression of Krt10 and Fabp5 in MmuPV1 tumor tissues." (PMID 34343212, 2021). "We then explored the correlation between FABP5 expression and tumour recurrence." (PMID 33837625, 2021). "Interestingly, PD-L1 blockade decreases FABP4 and FABP5 expression in tumor cells while upregulating expression of these molecules in TRM cells, promoting TRM cell survival and their antitumor response." (PMID 33922441, 2021).
tumor (continued). "Moreover, colony formation assays, matrigel invasion assays and wound healing assays were carried out to further study the function of FABP5 on tumour malignant biological behaviour in LGGs." (PMID 33837625, 2021). "Considering the previously reported links between lipid metabolism and tumor progression, we hypothesized that FABP5/HIF-1α plays a crucial role in cancer development." (PMID 33128030, 2020). "FABP3 is a tumor suppressor, whereas FABP4, FABP5, and FABP7 are associated with poor survival." (PMID 31941087, 2020). "On the basis of our in vivo and in vitro co-culture and EET-supplementation experiments, we hypothesized that inhibiting FABP4 and FABP5 is critical in attenuating EET-driven TNBC tumor growth, relapse, and metastasis." (PMID 31941087, 2020). "Moreover, tumours in the FABP5 overexpression group were of greater weight and size than control groups." (PMID 32550890, 2020). "The overexpression of FABP5 was also reported in many types of tumor." (PMID 32579175, 2020). "We hypothesized that FABP4 and FABP5 are critical nodes for EET-driven TNBC oncogenic signaling because these lipid chaperone proteins are upregulated in metastatic TNBC tumor specimens overexpressing CYP epoxygenases (CYP2C19)." (PMID 31941087, 2020). "Besides, it was also demonstrated that the expression level of both FABP4 and FABP5 was downregulated by treatment with berberine in tumor tissues of MGC803 xenografts." (PMID 32328135, 2020). "We further examined the expression of FABP5 and downstream molecules in subcutaneous tumours." (PMID 32550890, 2020). "Importantly, a significant inverse correlation between FABP5 and miR-144-3p was found in CCa tumours." (PMID 32550890, 2020). "Interestingly, the OA-treated tumor spheroids exhibited greater expression of FABP5 and HIF-1α and grew faster compared with vehicle-treated spheroids; this was abrogated by FABP5 or HIF-1α knockdown." (PMID 33128030, 2020). "FABP5 expression presented in both adjacent tissue and tumor core of NSCLC." (PMID 32611686, 2020). "To validate whether FABP5 plays a role in LNM, we first analysed the expression of FABP5 mRNA and protein in CCa tumours." (PMID 32550890, 2020). "Strikingly, knockdown of FABP5 dramatically inhibited tumour-associated LNM in vivo, suggesting that FABP5 may represent a potential molecular target for clinical intervention in CCa patients." (PMID 32550890, 2020). "Importantly, FABP5 overexpression enhances tumor growth and metastasis while pharmacological or genetic FABP5 inhibition suppresses PCa metastasis." (PMID 31831821, 2019). "Even so, treatments targeting FABP5 or patients’ diets might provide meaningful opportunities for tumor therapeutic strategies." (PMID 30948929, 2019). "Di-Poi demonstrated that activation of PPARβ/δ could significantly repress the expression level of PTEN, indicating FABP5 might participate in the tumor progress via mediating its FA metabolism." (PMID 30948929, 2019). "Compared to FASN-overexpressing cells, knockdown of FABP5 in FASN-overexpressing cells (FASN/shFABP5) significantly reduced luciferase signal in the primary tumor, whole mouse, and femurs in vivo, confirming that FABP5 knockdown suppresses the ability of FASN to promote metastasis." (PMID 31831821, 2019). "Vector-expressing PC3-Luc cells (Vector) developed tumors that gradually metastasized to femurs while knockdown of FABP5 (shFABP5) reduced signal at the primary tumor, whole mouse, and femurs, confirming that FABP5 inhibition reduces tumor growth and metastasis." (PMID 31831821, 2019). "Indeed, we found that FABP5 knockdown significantly inhibited the gene expressions of fatty acid-metabolizing enzymes and invasive activity of tumour cells." (PMID 31427660, 2019). "Our research revealed the potential tumor-promoting effect of FA transport protein FABP5." (PMID 30948929, 2019).